ADAM6 (ADAM metallopeptidase domain 6 (pseudogene))
Synonyms: ADAM6P; tMDCIV; formerly C14orf96
Gene: Transcribed unprocessed pseudogene on chromosome 14 (105,970,168 to 105,971,166, reverse strand). Ensembl gene ENSG00000271968.
Diseases named in the same sentence as ADAM6 in open-access papers:
ADAM6 is named in the same sentence as 20 diseases in open-access papers, as found by Europe PMC text mining. Sharing a sentence is not in itself a finding about the gene and the disease. The quoted sentences say what the papers report.
acute lymphoblastic leukemia (2 papers, 2021 to 2025). Leukemia with an acute onset, characterized by the presence of lymphoblasts in the bone marrow and the peripheral blood. "A Disintegrin And Metalloproteinase Domain-6 (ADAM6), a member of ADAMs family, has emerged recently as a potential novel player in pediatric acute lymphoblastic leukemia (ALL), and its function remains largely elusive." (PMID 40382561, 2025).
melanoma (2 papers, 2018 to 2025). A malignant, usually aggressive tumor composed of atypical, neoplastic melanocytes. "It is reported that an exploratory biomarker panel derived from ADAM6 conferred prognostic utility for melanoma recurrence and death." (PMID 30587197, 2018).
sarcoma (2 papers, 2021 to 2022). A usually aggressive malignant neoplasm of the soft tissue or bone. "One bioinformatic analysis reported that the overexpression of the lncRNAs ADAM6, C5orf58, CXCR2P1, FCGR2C, HCP5, HLA-H, NAPSB, NCF1B, and NCF1C reduced the sensitivity of sarcoma to ICIs." (PMID 36326232, 2022). "The expression of nine ICLs, ADAM6, C5orf58, CXCR2P1, FCGR2C, HCP5, HLA-H, NAPSB, NCF1B and NCF1C, was further investigated in different cancer types, including sarcoma." (PMID 34178688, 2021).
acute leukemia (1 paper, 2025). A clonal (malignant) hematopoietic disorder with an acute onset, affecting the bone marrow and the peripheral blood. "As for acute leukemia, ROC curve for ADAM6 showed excellent diagnostic value (AUC = 1, sensitivity = 100%, specificity = 100%, cut-off criterion > 123.8 pg/mL and 95% confidence interval (CI) (0.972–1)." (PMID 40382561, 2025). "Thus, overall, ADAM6 can be regarded as a relatively good diagnostic biomarker in acute leukemia patients with a potential prognostic implication in ALL which requires further investigations in larger cohorts to be fully elucidated." (PMID 40382561, 2025). "Next, we carried out ROC analysis to evaluate the diagnostic potential of ADAM6 in acute leukemia." (PMID 40382561, 2025). "ADAM6 showed excellent diagnostic value in acute leukemia patients and its subtypes ALL and AML." (PMID 40382561, 2025). "Afterwards, to gain insights into the prognostic potential of ADAM6 for acute leukemia, we classified both AML and ALL patients based on the presence/absence of characteristic classical prognostic CDs." (PMID 40382561, 2025). "In the whole study cohort, including control subjects and acute leukemia patients, Serum levels of ADAM6 were found to be significantly negatively correlated with serum levels of PRSS1 (r = −0.4264, p < 0.0001)." (PMID 40382561, 2025). "Both ADAM6 and PRSS1 exhibited a strong potential as novel diagnostic biomarkers for acute leukemia." (PMID 40382561, 2025). "Conclusively, the results of the current study portray ADAM6 and PRSS1 as potential novel diagnostic/prognostic biomarkers and therapeutic targets in acute leukemia." (PMID 40382561, 2025). "Interestingly, ADAM6 serum levels were found to be significantly higher while PRSS1 serum levels were found to be significantly lower in acute leukemia patients compared to their control counterparts." (PMID 40382561, 2025). "The results of the current study portray ADAM6 and PRSS1 as new potential diagnostic/prognostic biomarkers and potential therapeutic targets in adult acute leukemia patients, and shed light on their role as novel interrelated mediators possibly implicated in tumor micro-environment remodeling." (PMID 40382561, 2025). "Higher circulating ADAM6 and lower circulating PRSS1 levels were observed in acute leukemia patients compared to healthy control subjects." (PMID 40382561, 2025). "In the current study, we sought to determine the serum levels of ADAM6 and PRSS1, novel potential biomarkers with emerging implications in leukemogenesis, in adult patients with de novo acute leukemia compared to apparently healthy subjects." (PMID 40382561, 2025). "Further, in-depth thorough molecular studies are warranted to elucidate the mechanism of action of ADAM6 and PRSS1 in acute leukemia, and also to study their possible role and interrelation in other hematological malignancies and solid tumors." (PMID 40382561, 2025). "However, the findings of the current study provide a proof-of-principle, opening the door for future large-scale clinical studies to further elucidate the role of ADAM6 and/or PRSS1 in acute leukemia, as well as other types of cancer." (PMID 40382561, 2025). "Additionally, the current study adopted a cross-sectional design in which the levels of ADAM6 and PRSS1 were measured in patients with acute leukemia and control subjects at one time point and cannot detect a cause-effect relationship." (PMID 40382561, 2025). "Interestingly, ADAM6 and PRSS1 were found to be significantly negatively correlated with each other in the whole study cohort, including controls and acute leukemia patients." (PMID 40382561, 2025). "Furthermore, it’s important to point here that upon analysis of publicly available TARGET datasets for much larger cohorts of AML and ALL; ADAM6 and PRSS1 exhibited the same observed pattern of differential expression in acute leukemia patients compared to normal controls." (PMID 40382561, 2025).
acute myeloid leukemia (1 paper, 2025). Acute myeloid leukemia (AML) is a group of neoplasms arising from precursor cells committed to the myeloid cell-line differentiation. "Thus, this study was designed to investigate the roles of ADAM6 and PRSS1 in ALL and acute myeloid leukemia (AML) in adults." (PMID 40382561, 2025).
chronic myeloid leukemia (1 paper, 2021). "Since MIR-574/3P gene is known to suppress proliferation and induces apoptosis of chronic myeloid leukemia (CML) cells via targeting IL6/JAK/STAT3 pathway, the findings of this study provide novel insights into the association of ADAM6 with miR-574-3p signaling pathway in leukemia." (PMID 34249950, 2021).
colon cancer (1 paper, 2020). "Moonlight predicted ADAM6, a dual-role lncRNA, as a novel tumor suppressor in colon cancer and oncogene in head-and-neck cancer." (PMID 31900418, 2020).
gastric cancer (1 paper, 2019). A primary or metastatic malignant neoplasm involving the stomach. "The expression of the 5 other genes were found to be repressed by over-expressed non-coding RNA or by aberrant methylation of the promoter: GALNT5 in gastric cancer, ADAM6 in lung adenocarcinoma, PIWIL1 and PIWIL4 in lung adenocarcinoma and renal cell carcinoma." (PMID 31568528, 2019).
glioma (1 paper, 2021). A benign or malignant brain and spinal cord tumor that arises from glial cells (astrocytes, oligodendrocytes, ependymal cells). "ADAM6 is often upregulated in cancers including glioma, and its expression was high in GBM and lower in ODG and correlated to poor outcome in lower-grade glioma." (PMID 33981597, 2021). "The CNA gains of LINC00226 and ADAM6 and the chromosome 16p11 loss were reconstituted in primary cells from both grade II/III gliomas and GBMs." (PMID 33981597, 2021).
Hypertension (1 paper, 2013). The presence of chronic increased pressure in the systemic arterial system. "Among the highly down-regulated genes in the MCA of the hypertension group were SST, ADAM6, and PRLR." (PMID 23874591, 2013).
cancer (8 papers, 2018 to 2025). A tumor composed of atypical neoplastic, often pleomorphic cells that invade other tissues. "In this study, we investigated the germline mutation alterations of ADAM6, SIX3, GNAS, NDUFV1, H19, DEFA4, and ZIM2 genes in 82 pediatric cancer patients treated with cisplatin." (PMID 41009448, 2025). "The Brazilian series, which mostly included HPV-positive tumors, proposed targeting ADAM6 alterations involved in the Notch pathway, although there is little knowledge of their role in cancer." (PMID 35008677, 2021). "We also detected another five smRMGs that mutated in nearly half of the samples in corresponding cancers, including PCDHAC2 in SKCM (53%), ZFPM1 in ACC (52%), VHL in KIRC (49%), GNAQ in UVM (49%), and ADAM6 in LUSC (45%)." (PMID 30107644, 2018). "Among those genes, we focused on KCNA2, TNFRSF13B and ADAM6, which exhibit a 11x, 7x and 3.5x fold increase respectively, since they were among the 9 differential expressed genes with p values <0.00001 that have a clearer biological role in cancer." (PMID 35990685, 2022). "Thus, both ADAM6 and PRSS1 can modulate several signaling cascades interrelated with leukemogenesis and cancer progression." (PMID 40382561, 2025). "On the other hand, several members of the ADAMs family have been regarded as non-proteolytic mediators and considered as probable pseudogenes, including ADAM6, located in chromosome 14 (14q32.33) whose function in normal physiology or cancer has not been adequately studied." (PMID 40382561, 2025). "Furthermore, this is consistent with the hypothesized role of ADAM6, like other ADAM family members, to serve in autocrine and paracrine transactivation of the epidermal growth factor receptor (EGFR); an oncogene acting as key player in cancer development and progression." (PMID 40382561, 2025).
tumor (4 papers, 2020 to 2025). "ADAM6 was found to be significantly upregulated while PRSS1 was found to be downregulated in TARGET AML tumor samples compared to normal samples." (PMID 40382561, 2025). "Also, in TARGET ALL samples, ADAM6 was found to be significantly upregulated in ALL tumor compared to normal (FC = 1.434, p ≤ 0.001), while PRSS1 was significantly downregulated in ALL tumor against normal samples (FC = −1.515, p ≤ 0.001)." (PMID 40382561, 2025). "Others, such as TNFRSF13B (member of the superfamily of TNF receptors) and ADAM6 (a member of the family of A disintegrin and metalloproteases) and contribute to a huge variety of biological processes such as cell growth, cell differentiation and metabolism and can participate in tumor promotion." (PMID 35990685, 2022). "Furthermore, both ADAM6 and PRSS1 are emerging novel mediators of extracellular matrix (ECM) and tumor micro-environment (TME) remodeling." (PMID 40382561, 2025). "ADAM6 was found to be significantly upregulated in TARGET AML tumor samples compared to normal (FC = 1.144, p ≤ 0.001), while PRSS1 was found to be downregulated in TARGET AML tumor samples compared to normal samples (FC = −1.698, p ≤ 0.001)." (PMID 40382561, 2025).
ADAM6 also shares sentences with these, for which no sentence is quoted: head and neck cancer (1 paper); hematological malignancies (1); leukemia (1); lung adenocarcinoma (1); lymphoid cancer (1); Mendelian diseases (1); myeloid leukemia (1); renal cell carcinoma (1).